GATA4 (GATA binding protein 4)
Diseases named in the same sentence as GATA4 in open-access papers (continued):
Sharing a sentence is not in itself a finding about the gene and the disease.
myocardial infarction (20 papers, 2013 to 2024). Gross necrosis of the myocardium, as a result of interruption of the blood supply to the area, as in coronary thrombosis. "Experimental induction of myocardial infarction by left anterior coronary artery ligation in rats causes an increase in the DNA-binding potential of Gata4 within 2 weeks." (PMID 33193725, 2020). "Our previous study showed that Gata4 overexpression improved cardiac function after myocardial infarction in rat hearts." (PMID 39590198, 2024). "During the past two decades, we and several other researchers have reported that Gata4 overexpression (OE) by direct injection into the heart muscle improved cardiac function after myocardial infarction (MI) in the murine heart." (PMID 39590198, 2024). "Our previous study showed that Gata4 overexpression improved cardiac function after myocardial infarction in the rat heart." (PMID 39070633, 2024). "Collectively, these findings suggest that circSorbs1 modulates the expression of GATA4 by sequestering miR99, thereby regulating GATA4-mediated myocardial regeneration and facilitating post-myocardial infarction repair." (PMID 39080192, 2024). "There remain unresolved questions about the biological significance of c-Kit and GATA4 in the CPC-mended broken heart after myocardial infarction." (PMID 32517655, 2020). "Nkx2.5 or GATA-4 were transfected into myocardial extracellular environment co-cultured BMSCs, and then injected into the periphery of infarcted myocardium of a myocardial infarction rabbit model." (PMID 25975979, 2015). "In this study, hEGCs were transplanted into the infarcted zone of rats with myocardial infarction and 1 day and 1, 2 and 4 weeks later, positive expression of GATA-4 was observed in the progenitor cells, mainly in the nuclei." (PMID 24520255, 2014). "Two recent reports demonstrated that following myocardial infarction delivery of Gata4, Mef2c, and Tbx5, or GATA4, HAND2, MEF2C, and TBX5 in the injured myocardium successfully reprogrammed cardiac fibroblasts into cardiomyocytes." (PMID 23704920, 2013). "In addition, exogenous gene transfection of Nkx2.5 or GATA-4 into myocardial cell extracellular environment co-cultured BMSCs was able to enhance the ability to repair, mitigate the death of the myocardial cells and activate myocardium in myocardial infarction-induced rabbits." (PMID 25975979, 2015). "In this study, we investigated whether the activation of ORL1 without Gata4 administration improved cardiac function after myocardial infarction, thus inhibiting HF progression." (PMID 39590198, 2024). "This study aimed to investigate whether exosomes secreted by mouse GATA-4-expressing bone marrow mesenchymal stem cells (BMSCs) could induce BMSC differentiation into myocyte precursors, decrease cardiomyocyte apoptosis, and improve cardiac function following myocardial infarction (MI)." (PMID 29899566, 2018). "Echocardiography showed that GATA4-Exo treatment preserved LV function, as indicated by the end-systolic chamber volume (ESCV) and end-systolic left ventricular internal diameter (LVID) after myocardial infarction, but NC-Exo treatment did not." (PMID 32586406, 2020).
cardiomyopathy (19 papers, 2012 to 2025). A disease of the heart muscle or myocardium proper. "For example, heterozygous Gata4 mutations in mice can cause endocardial cushion defects, atrial or ventricular septal defects, hypoplastic right ventricle, or cardiomyopathy depending on genetic background." (PMID 36929416, 2023). "In human, missense mutations in GATA4 are associated with multiple heart diseases such as cardiac septal defects and cardiomyopathy." (PMID 32912314, 2020). "Moreover, in vitro studies suggest that PKGIα activation influences GATA Binding Protein 4 (GATA4), a transcription factor crucial for human cardiac muscle development, with structural and functional alterations linked to cardiomyopathies." (PMID 40429695, 2025). "With regards to GATA4, mutations in the GATA4 gene were shown to cause congenital cardiomyopathies." (PMID 35563646, 2022). "Accordingly, Gata4 null mice show cardiac defects that result in embryonic lethality and genetic variants affecting GATA4 activity have been associated with a range of cardiac defects including right ventricular hypoplasia and cardiomyopathy." (PMID 33803193, 2021). "Together, our results suggest that the downregulation of the GATA4 and associated proteins could in part explain the development of cardiomyopathy in diabetes." (PMID 22474596, 2012). "Our findings suggest that in addition to impacting the interaction of GATA4 with TBX5, the G296S mutation can also alter PGC-1α/ERRγ/GATA4 cooperativity which could contribute to the human disease phenotypes including cardiomyopathy which occurs in ERR-deficient mice." (PMID 35418170, 2022). "Transgenic overexpression of GATA4 results in severe cardiomyopathy and early death in mice and acute hemodynamic stress due to bilateral nephrectomy increases ventricular BNP reporter expression through a GATA4-dependent pathway." (PMID 29970016, 2018). "It is reported that EPO restored and augmented extracellular signal-regulated kinase (ERK) activity and activated ERK phosphorylated GATA-4 to enhance its DNA binding and transcriptional activation in cardiomyopathy models." (PMID 22954171, 2012). "Reduced expression of GATA4, a transcriptional factor for structural and cardioprotective genes, has been proposed as a factor contributing to the development of cardiomyopathy." (PMID 22474596, 2012). "Artificial intelligence tools and integrative data analysis revealed superoxide dismutase, catalase, glutathione peroxidase, gap junction protein α, myosin heavy chains, and zinc finger transcription factor GATA4 are engaged in oxidative stress and in cardiomyopathy." (PMID 35311161, 2022). "GATA4 mutations are known causes for cardiac septal defect but not for cardiomyopathy, even less ventricular noncompaction." (PMID 30690934, 2019). "Our results indicate that low GATA4 in db/db mouse heart is accompanied by reduced expression of GATA4-regulated cardioprotective and structural genes, which may explain the development of cardiomyopathy in diabetes." (PMID 22474596, 2012). "Based on this evidence, low GATA4 levels in the db/db heart would suggest that the documented cardiomyopathy in this model of diabetes may be accompanied by a downregulation of GATA4-regulated structural and cardioprotective genes." (PMID 22474596, 2012).
gastric cancer (18 papers, 2010 to 2025). A primary or metastatic malignant neoplasm involving the stomach. "Yamamura’s research demonstrated that hyperacetylated status occurred in histones H3 and H4 in the GATA4-positive gastric cancer cells, using CHIP assay." (PMID 40963862, 2025). "Interestingly, GATA4 is amplified in esophageal adenoma and gastric cancer and possesses oncogenic properties." (PMID 34987705, 2021). "In colorectal and gastric cancer cell lines, GATA4 and GATA5 genes and their target genes including DAB2 promoter were found to be hypermethylated, suggesting epigenetic silencing may be responsible for loss of DAB2 protein expression in these cell lines." (PMID 20525238, 2010). "The family member ELF3 was well expressed in the mRNA level in a subset of gastric cancers (n = 91), and its expression correlated with the expression of other transcription factors involved in gastric cancer pathogenesis, including HNF4A, HNF1A, CDX2, GATA4, GATA6, and EHF." (PMID 41425714, 2025). "Specifically, the methylation of GATA4 and GATA5 has been frequently observed in gastric cancer, which suggests that these genes may be tumor suppressors." (PMID 27598141, 2016). "Were showed that methylation of GATA4 (23.2%) occurs not at so high frequencies in glioblastoma as in colorectal cancer (70%) or sporadic gastric carcinomas (53.8%)." (PMID 23320456, 2013).
lung carcinoma (18 papers, 2009 to 2024). "It has been shown that the hypermethylation of GATA4’s promoter leads to the loss of its expression, which has been observed in several types of cancers, such as colorectal, gastric, and lung cancers." (PMID 37372326, 2023). "GATA4 can promote the aging of lung cancer cells, and reduced GATA4 expression levels are associated with poor lung cancer prognosis." (PMID 33315534, 2021). "We find that GATA4 is an essential TSG and further demonstrate that the hyperactivated TGF-β-TGFBRs-SMAD-Wnt signaling axis serves as potential target for treating GATA4-deficient lung cancer." (PMID 30971692, 2019). "Our data has shown that TGFB2-WNT7 signaling axis is hyperactivated in GATA4-deficient lung cancer cells." (PMID 30971692, 2019). "TGFBR1 inhibitors show synergy with existing therapeutics in treating GATA4-deficient lung cancers in genetically engineered mouse model as well as patient-derived xenograft (PDX) mouse models." (PMID 30971692, 2019). "We went on to treat GATA4-deficient lung cancer through targeting TGFBR1 using transgenic mouse models." (PMID 30971692, 2019). "GATA4 mutations have also been demonstrated in breast, ovarian, and lung cancers." (PMID 37372326, 2023). "Thereby, effective inhibitors targeting this signaling axis could potentially be employed for treating GATA4-deficient lung cancer patients." (PMID 30971692, 2019). "Moreover, we showed that TGFBR1 inhibition could suppress the malignant progression of GATA4-deficient lung cancer." (PMID 30971692, 2019). "Another example is that the transcription factor and known tumor suppressor GATA4 inhibits WNT7B expression via TGF-β signaling in murine lung cancer models." (PMID 36982422, 2023). "GATA4 probably suppresses lung cancer through the TGF-β2/Wnt7B signalling pathway, and GATA deficiency blunted the therapeutic effect of MEK1/2 inhibition in a mouse model." (PMID 35936012, 2022). "GATA4 expression was consistently reduced in human lung cancer cell lines compared with normal lung epithelial cell lines and decreased GATA4 level in clinical specimens predicted poor prognosis." (PMID 34093794, 2021). "As GATA4 inactivation was reported in more than half of all clinical lung cancer cases, special attention should be paid to the status of GATA4 function for precision medicine for lung cancer patients." (PMID 30971692, 2019). "Tumor suppressive function of GATA4 was further confirmed in transgenic mouse models for lung cancer in vivo." (PMID 30971692, 2019). "Collectively, our work demonstrates that GATA4 functions as a tumor suppressor in lung cancer and targeting the TGF-β signaling provides a potential way for the treatment of GATA4-deficient lung cancer." (PMID 30971692, 2019). "Together, these data showed that TGF-β2 functioned upstream of Wnt-7b in mediating GATA4-induced senescence of lung cancer cells." (PMID 30971692, 2019). "Since GATA4 induces lung cancer cell senescence through downregulating WNT7B, we checked PML-HIRA colocalization signal triggered by ectopic expression of GATA4." (PMID 30971692, 2019). "By downregulating TGFB2 level via miRNAs, GATA4 decreases expression of WNT7B to induce senescence in lung cancer cells." (PMID 30971692, 2019). "Despite of the fact that GATA4 is widely epigenetically silenced in lung cancer, the impacts of GATA4 silencing on tumorigenesis and corresponding cancer therapeutic strategies remain largely unexplored." (PMID 30971692, 2019). "We here performed a genome-wide screening of TSG TFs in lung cancer and identified GATA4 as an important tumor suppressor." (PMID 30971692, 2019). "Through the genome-wide screening of tumor-suppressive transcription factors, we demonstrate here that GATA4 functions as an essential tumor suppressor in lung cancer in vitro and in vivo." (PMID 30971692, 2019). "Taken together, these data suggest that GATA4 is frequently downregulated in lung cancers and the TGFB2-WNT7B signaling in these samples are activated." (PMID 30971692, 2019).
lung carcinoma (continued). "We went on to confirm tumor suppressor function of GATA4 in vivo using transgenic lung cancer mouse model." (PMID 30971692, 2019). "BMP4 functions as a pro-tumorigenic factor in a murine lung cancer model, and its transcription is regulated by miR-200 and GATA4/6." (PMID 26395571, 2015). "In summary, BMP4 functions as a pro-tumorigenic factor in a murine lung cancer model and is regulated by miR-200 and GATA4/6." (PMID 26395571, 2015). "Knockdown of WNT7B in lung cancer cell lines could phenocopy the senescence-inducing effect of ectopic GATA4 expression, while WNT7B overexpression could rescue this effect." (PMID 36982422, 2023). "The tumor suppressor GATA4 is frequently epigenetically silenced in lung cancer." (PMID 30971692, 2019). "Taken together our data, we showed that GATA4 is frequently inactivated in lung cancer cells." (PMID 30971692, 2019). "However, knockdown of p15INK4b expression with shRNAs failed to rescue cell from GATA4-induced senescence, suggesting that GATA4 induced senescence in lung cancer cells independently of canonical pathway." (PMID 30971692, 2019). "GATA4 inactive lung cancers tend to have hyperactive TGB2-WNT7B signaling axis." (PMID 30971692, 2019). "Ectopic GATA4 expression results in lung cancer cell senescence." (PMID 30971692, 2019). "We next investigated how GATA4 influenced lung cancer cell growth." (PMID 30971692, 2019). "We therefore focused on GATA4.Western blot analysis showed that GATA4 expression in human lung cancer cell lines including NCI-H226, NCI-H23, NCI-H460, PC9, and A549 cells was consistently lower than normal lung epithelial cell lines including HSEAC37, HSEAC2KT, and HBEC30." (PMID 30971692, 2019). "GATA4 is an important tumor suppressor in lung cancer and could induce the senescence of lung cancer cells via upregulating several miRNAs that target TGFB2 mRNA and ensuing downregulation of WNT7b expression, suggesting WNT7b may play a carcinogenic role in lung cancer." (PMID 37486552, 2023). "Bulk tumor RNA-seq of somatically edited tumors in the autochthonous KPC model of lung cancer showed numerous changes in the microenvironment of sgGata4-targeted tumors; however, it is not clear which changes can be directly attributed to cells in which Gata4 was edited." (PMID 35017504, 2022). "We asked whether this axis can be employed for treating GATA4-low lung cancers." (PMID 30971692, 2019). "Finally as Gata4 is dispensable for integrity of the adult lung, it may be an ideal target for development of future treatment regimens to treat lung cancer provided that therapy can be targeted to lung." (PMID 19551151, 2009). "GATA1, GATA4 and GATA5 were exceptionally downregulated in lung cancer cell lines, including SCLC and NSCLC." (PMID 34093794, 2021). "Promoter methylation of eight lung cancer-specific genes (CDO1, TAC1, SOX17, HOXA7, HOXA9, GATA4, GATA5, and PAX5) was detected using nanoparticle-based DNA extraction (MOB) followed by qMSP." (PMID 32138766, 2020). "Our model predicts that GATA4 expression level is inversely correlated with those of TGFB2 and WNT7B in lung cancer." (PMID 30971692, 2019). "Our above data have shown that GATA4 expression downregulated TGFB2 and the ensuing downstream WNT7B signaling in A549 lung cancer cell line." (PMID 30971692, 2019). "The aberrant expression or DNA modification of GATA-2, GATA-4, GATA-5, and GATA-6 was found in lung cancer, but GATA-1 gene expression is seldom reported in LADC." (PMID 29100282, 2017). "The other genes AR, ATF2, CUL1, EP300, GATA4, LEF1, SKP2 in these subnetworks have also been identified as important in lung cancer." (PMID 24369052, 2013). "Due to unbalanced sample distribution (not enough GATA4-high lung cancer samples), we were not able to calculate the significance in correlation test." (PMID 30971692, 2019).
lung carcinoma (continued). "We also supplemented Dox-treated A549i cells with recombinant TGF-β protein and found that TGF-β protein rescued GATA4-induced senescence of A549 cells in a dose-dependent manner, supporting that TGF-β protein itself prevented GATA4-induced senescence in lung cancer cells." (PMID 30971692, 2019). "To confirm whether GATA4-induced senescence was common in lung cancer cells, we generated lung cancer cell lines (H460, EKVX, and HOP62) for Dox-inducible expression of GATA4." (PMID 30971692, 2019). "Clinical studies reported frequent hypermethylation of the GATA4 promoter in human lung cancer samples but not in paired normal lungs." (PMID 30971692, 2019). "Frequent hypermethylation of the GATA4 promoter in majority of lung cancer samples but not in normal human lung tissues has been reported." (PMID 30971692, 2019). "We found that cisplatin was partially effective in shrinking both GATA4-high and GATA4-low lung cancer PDX tumors, while SB525334 alone was not effective in either group." (PMID 30971692, 2019). "Conversely, knockdown of GATA4 expression level upregulated TGFB2 and WNT7B transcription in lung cancer cell line H226, supporting that GATA4-TGF-β2-Wnt-7b signaling axis is common to lung cancer cells." (PMID 30971692, 2019). "However, this actually fitted our conclusion more favorably: GATA4 is inactive and at the same time WNT7B and TGFB2 is hyperactive in lung cancer cells." (PMID 30971692, 2019). "Of note, we found that GATA4 knockdown or overexpression did not significantly impact epithelial–mesenchymal transition of lung cancer cells in vitro and in vivo, consistent with earlier reports that TGFBR-SMAD signaling axis affect the senescence." (PMID 30971692, 2019). "Likewise, treatments with β-Catenin inhibitors, XAV93937 and ICG-00138, respectively, did not lead to increased senescence, suggesting that canonical Wnt signaling is not responsible for GATA4-induced lung cancer cell senescence." (PMID 30971692, 2019). "However, we did not detect obvious upregulation of SASP cytokines in lung cancer cells ectopically expressing GATA4." (PMID 30971692, 2019). "Interestingly, we found that GATA4 expression resulted in similar level of PML-HIRA colocalization to that found in WNT7B knockdown, suggesting that mechanism revealed by Adams and colleagues may apply to GATA4 induced senescence in lung cancer cells." (PMID 30971692, 2019). "We also found significant negative correlation of expression level between GATA4 and TGFB2 and between GATA4 and WNT7B among non-manipulated lung cancer cell lines and normal lung epithelial cell lines." (PMID 30971692, 2019).